KRAS (KRas proto-oncogene, GTPase)
Diseases named in the same sentence as KRAS in open-access papers (continued):
Sharing a sentence is not in itself a finding about the gene and the disease.
colon carcinoma (continued). "Likewise, BRAF, a major downstream effector of KRAS, is also considered an oncogene whose activating mutations appear in 70% of human malignant melanomas and in about 12-18% of human colon cancers." (PMID 21943101, 2011). "Since KRAS analysis is now widely available due to its application as a predictive marker for anti-EGFR therapy in colon cancer, this diagnostic tool could also be applied to help the clinician in managing pancreatic masses." (PMID 24212643, 2011). "The role of KRAS mutation status in clinical decision making is best defined for colon cancer." (PMID 21110880, 2010). "However, fewer than 50% of colon tumors harbor KRAS mutations, and the relationship between Ras signaling and hypoxia in tumors with wild-type KRAS remains undefined." (PMID 20532039, 2010). "However, KRAS mutations are identified in less than half of all colon cancers, and the role of wild-type KRAS in the hypoxic response is less certain." (PMID 20532039, 2010). "However, it should be acknowledged that the intrinsic mechanism of these cytokines in remodeling TME in KRAS mutated colon cancer remains unknown, further studies are required." (PMID 38097680, 2023). "In addition to the different mutation subtypes of KRAS, colon cancer patients also possessed other comutations which might contribute to the occurrence and development." (PMID 38097680, 2023). "In addition, the in silico cell-line-toxicity prediction suggests that our four leads could possess cytotoxicity against the pancreatic, lung, and colon cancers in which the KRAS is highly mutated." (PMID 36975507, 2023). "Taken together with the previous studies, the present findings suggest that the ability of reagents that interfere with PCs, particularly Furin, could potentially have therapeutic effects by regulating calcium regulators in colon cancer with KRAS or BRAF mutation." (PMID 35267511, 2022). "Microsatellite stable colon cancer models with BRAF or KRAS mutations in Subgroups II and IV have shown responses to the combination of EGFR (cetuximab), MEK (trametinib), and/or RAF (regorafenib) inhibition, providing a strong hypothesis for further evaluation." (PMID 34885128, 2021). "Arterial CTCs and venous CTCs of patients with colon cancer can detect more mutated genes than tissue, and arterial CTCs can detect the mutated genes targeted with clinically available drugs (Fbxw7), while tissues can also detect the mutated genes targeted with clinically available drugs (KRAS)." (PMID 34134721, 2021). "Therefore, we predicted that KRAS mutations play an important role in colon cancer." (PMID 33254149, 2020). "In the present case, small intestinal and colon cancer specimens harbored identical KRAS mutations, suggesting that finding aberrant predictive biomarkers is also a potent diagnostic strategy to determine whether the multiple cancers derived from a single clone." (PMID 32867793, 2020). "Furthermore, statistical analysis showed that the circRNA_100859-miR-217-HIF-1α axis was associated with Tumor-Node-Metastasis (TNM) stage, histological grade, and KRAS mutations, and also showed high diagnostic and prognostic value for patients with colon cancer (P<0.05)." (PMID 32644049, 2020). "We have next evaluated whether Ab3‐8 inhibits tumor growth of KRAS‐mutated colon cancer cells." (PMID 31709772, 2020). "Because KRAS mutational status could partially determine the biological aspect in colon cancer, we compared the mutations detected in plasma and clinicopathological parameters in patients with KRAS mutation‐positive with those in patients with KRAS mutation‐negative." (PMID 30575318, 2019).
colon carcinoma (continued). "Therefore, developing therapies against KRAS-mutated colon cancer is an important, unmet need." (PMID 28800074, 2017). "In the proximal colon cancer network, KRAS mutation tended to be mutually exclusive only with BRAF mutation, indicating that the observed negative correlations of KRAS mutation with methylation-related markers and other biomarkers might be confounded by MSI-high in our earlier analysis." (PMID 28623901, 2017). "BKM120 may overcome cetuximab resistance in colon cancer cells with KRAS mutation." (PMID 26715098, 2016). "Indeed, the presence of KRAS-mutated CTCs in patients with KRAS wild-type primary colon carcinomas might be one explanation for failure of drug-mediated EGFR inhibition in these patients." (PMID 25398926, 2015). "Interestingly, when stage II colon and rectal tumours were analysed separately, only the presence of a KRAS mutation in colon cancers was associated with a trend towards a worse DFS (HR, 3.64; P=0.07), and these results were maintained in the Cox regression analysis (HR, 4.163; P=0.07)." (PMID 20959826, 2010). "The tumors here investigated were selected based on potential EGFR treatment, which may bias the results toward tumors prone to metastatic development, though the overall KRAS mutation frequency of 39% and the relation between colon cancer and rectal cancer are as expected." (PMID 19832985, 2009). "KRAS wild-type was detected in 26 (46.4%) patients with left-sided colon cancer and in 5 (71.4%) patients with right-sided colon cancer." (PMID 40587729, 2025). "Menaquinone or vitamin K2 was found to reduce KRAS proliferation in colon cancer cells and promote apoptotic cell death in CRC mice." (PMID 39641861, 2025). "To determine the connection between REGγ expression and clinical outcomes in cancers with KRAS mutations, we examined REGγ expression in human colon cancer tissues, including the KRAS-MUT subgroup (n = 10) and the KRAS-WT subgroup (n = 14)." (PMID 40091835, 2025). "The KRAS G12C inhibitor, Sotorasib, has shown benefit in patients with non-small-cell lung cancer and colon cancer." (PMID 41155343, 2025). "Although the EGFR pathway is considered unresponsive to treatment in patients with KRAS mutations, recent research in 2025 found that EGFR still plays an active role in colon cancer cells with KRASG12D mutations." (PMID 41226554, 2025). "KRAS mutations were noted to be the most common mutation in HER2-amplified CRC (21.8%, 19/87), with rates notably higher in HER2-amplified colon cancer (27.9%, 17/61) and lower in HER2-amplified rectal cancer (7.7%, 2/26)." (PMID 40742050, 2025). "Similar results were observed in the activating KRAS-mutant colon cancer cell line HCT116, where braftide reduced the CDC37–RAF interaction at lower doses than in HEK293 cells, suggesting this effect is not cell line specific." (PMID 41371342, 2025). "Case Presentation: We present a case report of a 68-year-old female patient with KRAS G12D and PIK3CA mutations who was diagnosed with stage IV-C colon cancer." (PMID 40710850, 2025). "Enhancing anti-EGFR efficacy of cetuximab by increasing ROS production in KRAS mutant colon cancer cell xenografts overexpressing SVCT2 (P < 0.05)." (PMID 40950984, 2025). "This compound was tested in different types of human cancer cell lines, including three colon cancer cell lines (HCT116 which was KRAS-mutated, and COLO205 and HT-29 which were KRAS-wildtype)." (PMID 40852028, 2025). "For example: the KRAS gene mutation presents a therapeutic difficulty for EGFR‐targeted therapies; so, other strategies are required to lower the failure rate in colon cancer therapy." (PMID 39803273, 2025).
colon carcinoma (continued). "KRAS is one of the targets for miR-155, and the probiotics treatment significantly increased KRAS expression level in the colon tumor." (PMID 41237260, 2025). "When applied to colon cancer cells that expressed either wild‐type or mutant KRAS genes, it showed effectiveness." (PMID 39803273, 2025). "In genetically engineered mice with KRAS-driven colon tumors, VC treatment led to fewer and smaller tumors." (PMID 40950984, 2025). "The pooled analysis of seven trials within the ACCENT/IDEA consortium explores the distinct prognostic implications of KRAS exon 2 submutations and the BRAF V600E mutation in stage III colon cancer." (PMID 38786299, 2024). "Our finding supplements the involvement of KRAS in this aggressive histological sub-type of colon cancer." (PMID 38229035, 2024). "Our findings confirm the complex interplay between genetic mutations and MSI status, emphasizing the nuanced role of MSI in modifying the prognostic implications of KRAS, NRAS, and BRAF mutations in colon cancer." (PMID 38786299, 2024). "To confirm the generalizability of this long-term transcriptional response, we developed and profiled two additional models of evolved resistance to dual-mechanism ERK inhibition in KRAS-mutant lung and colon cancer cells." (PMID 38822082, 2024). "This study specifically focused on the distribution of the mutation frequency of KRAS and BRAF genes across different clusters, which were important for targeted therapy in patients with colon cancer." (PMID 38327746, 2024). "We analyzed the changes in SLC7A7 and gene mutations, acquisitions, and deletions in colon cancer, the difference in APC, TTN, KRAS, SYNE1, RYR2, and LRP1 mutations was statistically significant." (PMID 39730571, 2024). "The patient had KRAS mutation and MSS-type colon cancer, and his PD-1+CD8+ and CD3-CD19-CD14+CD16-HLA-DR were both positive." (PMID 38617840, 2024). "This systematic review focuses on the prognostic significance of KRAS, NRAS, and BRAF mutations within MSI-H colon cancer." (PMID 38786299, 2024). "Apart from the low rate of KRAS mutations, in IBD associated colon cancer driver genes are the same as in sporadic colon cancer, but the timing of the mutations is different." (PMID 39359726, 2024). "In the comprehensive cohort analysis, PIK3CA exon 9 and 20 mutations were overrepresented in proximal colon cancer, CIMP-low (CIMP-L), and KRAS-mutated cancers." (PMID 39113889, 2024).
colon carcinoma (continued). "It has also been reported that EVs from KRAS mutant colon cancer cells transfer mutant KRAS to wild‐type cells resulting in their enhanced three‐dimensional growth." (PMID 39611045, 2024). "The mutually exclusive BRAF and KRAS mutations provide alternate means of activating the MEK-ERK signaling pathway and function as critical cancer driver mutations in colon cancers." (PMID 38360902, 2024). "PCSK9 blocking agents, especially when combined with statins, inhibit the neoplastic growth of APC/KRAS mutant colon cancer xenograft models by suppressing the KRAS/MEK/ERK pathway." (PMID 36900189, 2023). "We compared the KRAS OE score between different pathology stage, and we found that colon cancer patient with distant metastasis presented higher score while no trend revealed with the local progression of tumor." (PMID 38097680, 2023). "Application of the p38γ inhibitor pirfenidone (PFD) blocked p38γ-induced HSP90/S595 phosphorylation, promoted mutant KRAS degradation, and inhibited colon cancer xenograft growth in nude mice." (PMID 37443708, 2023). "The mutation of the KRAS gene promotes the activation of the MAPK pathway, which promotes the growth of colon cancer cells." (PMID 37020597, 2023). "MCl-062 was effective against HCT116 human colon cancer cells, which harbor KRAS G13D, and was ineffective against HT29 cells harboring BRAF V600E." (PMID 37569406, 2023). "The tumor’s Z-eff, λ, and MonoE values identified mutant versus wild-type KRAS genes in colon cancer to stage and histologically grade tumors." (PMID 37741813, 2023). "A KRAS related signature composed of 80 DEGs in colon cancer were recognized, among which 19 genes were selected to construct a prognostic model." (PMID 38097680, 2023). "RASA1 expression is significantly reduced in KRAS wild-type colon cancer cells, indicating that miR-21 activates the RAS signaling pathway by downregulating RASA1 expression." (PMID 37516822, 2023). "To exclude this possibility, we treated live ex vivo cultured colon tumor cells with rabbit anti-KRAS antibodies." (PMID 37051535, 2023). "In the case of colon cancer, the use of an MGO scavenger, carnosine, has shown promising results by enhancing the efficacy of cetuximab therapy in KRAS-mutated cancer cells." (PMID 37174618, 2023). "This leads to increased EGFR protein expression (due to p38γ) and enhanced EGFR de-phosphorylation (due to PTPH1), resulting in a phenotype of increased levels of un-phosphorylated EGFR proteins in KRAS-mutant colon cancer cells." (PMID 37443708, 2023). "A systematic review of nine randomized controlled phase III trials has revealed that KRAS and BRAF mutations are possible predictors of poor prognosis for stage II/III colon cancer treated with adjuvant chemotherapy." (PMID 37784019, 2023). "The sensors were used to detect KRAS in whole blood samples from colon cancer patients and results correlated well with KRAS detection in tumor tissue samples." (PMID 37764496, 2023). "Adagrasib 600 mg orally twice daily or adagrasib in combination with cetuximab (400 mg/m2 followed by 250 mg/m2 every week or 500 mg/m2 every 2 weeks) were regimens evaluated in cohorts with pretreated metastatic KRAS G12C-mutant colon cancer." (PMID 37569406, 2023). "This was mainly demonstrated in human colon cancer cells with a mutant KRAS gene, influenced by sodium-dependent vitamin C transporter 2 (SVCT-2) with administration of daily doses of 10 g of L-ascorbic acid for 6 h." (PMID 36979659, 2023).
colon carcinoma (continued). "In another study in colorectal cancel model, authors founded that PCSK9 induces oncogenesis in APC/KRAS mutant models of colon cancer and that systemic PCSK9 levels correlate with reduced survival in this patient cohort." (PMID 36900189, 2023). "The electrochemical sensors show promise as sensitive and selective tools for the minimally invasive detection of the colon cancer biomarker KRAS." (PMID 37764496, 2023). "We treated SW620 human colon cancer cells (homozygous KRAS G12V) to assess the effect of TUS-007 on cetuximab-resistant cancer cells and demonstrated dose-dependent KRAS G12V degradation." (PMID 37513471, 2023). "We also lacked data on tumor sidedness; prior literature has shown that RAS, KRAS, and BRAF mutations occur more frequently among right‐sided colon tumors than left‐sided colon tumors." (PMID 35837788, 2023). "For example, miR-143 has been shown to act as a tumor suppressor in NSCLC, cervical cancer, prostate cancer, ovarian cancer, colon cancer, and leukemia, being able to silence not only KRAS but also RAS-effector signal genes Erk and Akt." (PMID 37376135, 2023). "In conclusion, we identified and validated a KRAS related signature and comprehensively explored its role in characterizing genomic alteration, immune microenvironment and drug sensitivity of colon cancer." (PMID 38097680, 2023). "The three human RAS genes (KRAS, NRAS, and HRAS) are the most frequently mutated oncogenes in human cancers, occurring in 90% of pancreatic cancers, 35% of lung cancers, and 45% of colon cancers." (PMID 37228916, 2023). "To explore NOP56 functions in KRAS-mutant malignancies, we profiled the transcriptomic gene expression data of a previous study, whereby NOP56 in KRAS-mutant colon cancer cells (SW480) was silenced by siRNAs." (PMID 35039048, 2022). "CD107a externalization was evaluated as NKs/CD8 cytotoxicity toward human colon cancer cells HT29, SW620, HCT116, and LS174T carrying different KRAS mutations." (PMID 35936004, 2022). "We incorporate multi-omic molecular features to identify combination biomarkers and specify synergistic drug combinations and their active contexts, including in basal-like breast cancer, and microsatellite-stable or KRAS-mutant colon cancer." (PMID 35197630, 2022). "The combination of Axitinib and ABT263 exerted a synergistic effect on KRAS-mutant colon cancer cells by enhancing apoptosis." (PMID 36135086, 2022). "When SG formation was blocked using a COX-1/2 inhibitor in oncogenic KRAS-driven colon cancer cells, the cells also showed increased sensitivity to the chemotherapeutic drug oxaliplatin." (PMID 35147163, 2022). "The relationship between the KRAS expression level and PARPi efficacy in this study may provide a new direction for further preclinical trials of PARPi usage in such rare ovarian cancers and other malignancies with predominant KRAS mutations, such as colon cancer." (PMID 36230574, 2022).